LAG3 (lymphocyte activating 3)
Diseases named in the same sentence as LAG3 in open-access papers (continued):
Sharing a sentence is not in itself a finding about the gene and the disease.
colon carcinoma (52 papers, 2015 to 2025). "A recent study observed that upregulation of LAG-3 on tumor tissues was associated with a bad prognosis in patients with microsatellite instability-high colon cancer." (PMID 35455287, 2022). "LAG-3 expression in TILs was significantly associated with improved DFS in patients with stage II colon cancer." (PMID 35804964, 2022). "A recent study showed that overexpression of LAG-3 on tumor tissues was associated with worse prognosis in patients with microsatellite instability high (MSI-H) colon cancer." (PMID 35655158, 2022). "In conclusion, we were able to demonstrate that LAG-3 expression on TILs at the tumor front of stage II colon cancers was associated with better outcomes in both the overall stage II cohort and within the subgroup of stage II MSS tumors." (PMID 34442393, 2021). "Interestingly, the percentage of MMR-deficient colon cancers was higher if LAG-3 positive TILs were present in the tumor front or center." (PMID 34442393, 2021). "The NICHE-2 trial demonstrated the efficacy of Nivolumab + Ipilimumab therapy for resectable dMMR colon cancer, and the NICHE-3 trial reported the efficacy of Nivolumab + relatlimab, an anti-LAG-3 antibody, for resectable dMMR colon cancer." (PMID 41179285, 2025). "First, efficacy for ZGGS15 (only the anti-LAG-3 part is active in this model) plus anti-PD-1 in the BALB/c-hPD-1/hLAG-3 mouse bearing CT26 colon cancer model was performed." (PMID 38724599, 2024). "For this reason, we evaluated the potential of AU-011 combined with anti-PD-L1 and anti-LAG-3 antibodies using a metastatic murine tumor model of colon cancer." (PMID 36997666, 2023). "Firstly, to clarify the anti-tumor effect of YG-003D3, human PD-1/LAG-3 double knock-in mice Subcutaneous inoculated human PD-L1 knock-in MC38 colon carcinoma cell lines were used." (PMID 36518768, 2022). "In different types of cancer, such as lung, breast, stomach, ovarian, and colon cancers, LAG3-expressing T cells were increased in TILs." (PMID 35804964, 2022). "LSECtin, a ligand of immune checkpoint LAG3, has been shown to be an important factor in promoting liver metastasis of colon cancer." (PMID 36358719, 2022). "We performed SPECT/CT imaging on immunocompetent colon carcinoma–bearing mice using 99mTc-labeled LAG-3 single-domain antibody and compared tumor uptake values with a radiolabeled control single-domain antibody." (PMID 33712537, 2021). "Given the growing interest in the role of LAG-3 in cancer, we sought to evaluate the presence of LAG-3 on tumor-infiltrating lymphocytes (TILs) in the tumor center and tumor front and to assess its impact on outcomes in stage II colon cancer." (PMID 34442393, 2021). "Patients and Methods: Immunohistochemical staining for LAG-3 was performed on tissue microarrays (TMAs) of formalin-fixed paraffin-embedded tissue from 142 stage II colon cancer patients." (PMID 34442393, 2021). "Dual anti-LAG3/anti-PD-1 immunotherapy strikingly enhanced survival in the MC38 colon cancer model compared with animals treated with single antibodies alone." (PMID 25949894, 2015). "Notably, PRS exhibited a significant positive correlation with mRNA levels of immune checkpoint-associated molecules CD274, CTLA4, LAG3, and TIGIT in colon cancer tissues." (PMID 38577604, 2024). "Treg cells in human colon tumor tissues express immunosuppressive molecules such as PD-1, cytotoxic T-lymphocyte-associated protein-4 (CTLA-4), T cell immunoglobulin and mucin domain-3 (TIM-3) and lymphocyte-activation gene 3 (LAG-3)." (PMID 36982677, 2023). "Conversely, LAG3 mRNA expression was lower in the following: colon cancer (P < 0.001), kidney chromophobe (P < 0.001), liver cancer (P < 0.001), prostate cancer (P < 0.001), rectal cancer (P < 0.01), thyroid cancer (P < 0.05), and endometrioid cancer (P < 0.001), than in normal tissues." (PMID 38062416, 2023).
colon carcinoma (continued). "In left-sided colon tumors, low score of LAG3 in CT was significantly associated with no metastasis (P = 0.039), no recurrence (P = 0.027), and low tumor budding (P = 0.05)." (PMID 36765348, 2023). "LAG3 testing might aid in predicting outcomes for colon cancer patients and might help to find those who would benefit from adjuvant chemotherapy." (PMID 37142949, 2023). "Conversely, a lower ratio of MMR-deficient colon cancers was observed in the absence of LAG-3 positive TILs (p = 0.034)." (PMID 34442393, 2021). "The favorable association of LAG-3 expression on TILs either in the tumor front or tumor center with the outcome remained significant, even when we considered only MMR-proficient colon cancers (5-year DFS 90.2% versus 67.9%, HR 0.30, 95% CI 0.11–0.83, p = 0.014)." (PMID 34442393, 2021). "Expression of PD-1, LAG3 and T-bet was detected in lymphoid aggregates and scattered among the neoplastic glands, or at intra-epithelial sites, whereas LAG3 was also occasionally expressed by clusters of colonic cancer cells." (PMID 34975867, 2021). "We therefore hypothesized that LAG-3 expression on tumor-infiltrating lymphocytes (TILs) predicts outcome in patients with stage II colon cancer." (PMID 34442393, 2021). "We next sought to determine whether treatment with PI-3065 alone or in combination with LAG3-blockade, would enable control of other tumors, namely the colon carcinoma cell-lines, CT26 and MC38." (PMID 33093155, 2020). "Similarly, combined blockade of PD-1 and LAG-3 was required to achieve full tumor regression in murine models of fibrosarcoma and colon cancer." (PMID 25875653, 2015). "In contrast, CD27, CD276, LAG3, LGALS9, PDCD1, and TMIGD2 showed a highly enriched trend of expression with RFX1 in colon cancer." (PMID 41425715, 2025). "Subsequent studies have demonstrated impressive response rates to neoadjuvant PD-1 and CTLA-4 blockade (NICHE-2), and PD-1 and LAG-3 blockade (NICHE-3) in 113 and 59 patients with dMMR locally-advanced colonic cancer respectively." (PMID 41487587, 2025). "The PRS exhibited a significant positive correlation with the infiltration of diverse immune cells, expression levels of related cytokines, and mRNA levels of immune checkpoints CD274, CTLA4, LAG3, and TIGIT in colon cancer tissues." (PMID 38577604, 2024). "Anti-LAG-3 and anti-PD-1 ICB in combination with 5FU or GEM chemotherapy was an effective chemoimmunotherapy combination in mesothelioma and colon cancer preclinical models." (PMID 39343508, 2024). "IDO1, LAG3, and PD-L1 expression levels in TIICs showed a better prognosis for patients with MSI-H colon cancer." (PMID 36059952, 2022). "Therefore, LAG-3 may serve as a prognostic biomarker in stage II colon cancer." (PMID 34442393, 2021). "The immune checkpoint molecules CD274, LAG3, and IDO1 expressions in tumor-infiltrating immune cells showed a better prognosis for patients with MSI-H colon cancer." (PMID 34993132, 2021). "Consistently, dual inhibition of PD-1 and LAG-3 suppressed tumor growth more effectively than a single inhibitor in transplanted mouse models of Sa1N fibrosarcoma, MC38 or CT26-HER-2 colon carcinoma." (PMID 27835902, 2016). "Using a different tumor model of colon cancer, MC38, we expand on their data by showing the efficacy of AU-011 and ICI on distant tumors and identify the combination with anti-PD-L1 and anti-LAG-3 as the most suitable treatment regimen for both primary and distant tumors." (PMID 36997666, 2023). "In patients from the GEO dataset, BRAF mutation colon cancer also had higher expressions of CTLA-4 (p = 0.031) and LAG-3 (p = 0.0011), but had no significant expression of PD-1 (p = 0.58)." (PMID 34381786, 2021).
colon carcinoma (continued). "In addition, the anti-LAG-3/PD-L1 mAb2 was also used to reduce tumor burden in the MC38 colon cancer model, and there were more tumor-free animals in the LAG-3/PD-L1 bispecific group than in the combined anti-LAG-3 and anti-PD-L1 groups, which was similar to the CT26 mouse colon cancer model." (PMID 38581716, 2024). "In addition, higher numbers of LAG3 + TILs in IM correlated with higher T-stage, and low score of LAG3 in CT correlated with the absence of metastasis and recurrence in left-sided colon tumors." (PMID 36765348, 2023). "As opposed to the low-risk colon cancer patients, the high-risk cases showed higher expressions of CTLA-4 (p < 0.001), PD-1 (p < 0.01), PD-L1 (p < 0.001), IDO1 (p < 0.05), IDO2 (p < 0.05), HAVCR2 (p < 0.001), and LAG3 (p < 0.05)." (PMID 36280825, 2022). "Furthermore, the expression of LAG3 and PD-1 in healthy bowel tissues, colon cancer derived from normal (non-obesity) patients and obesity patients was confirmed by IHC." (PMID 33197880, 2020). "However, whether blocking CXCL8/CXCR1/2 signal or LAG3/LSECtin can increase the efficacy of anti-PD-1/PD-L1 or anti-CTLA4 in patients with colon cancer is still lack of effective experimental verification." (PMID 36358719, 2022). "For CRC, patients with non-metastatic dMMR colon cancer receiving around 6 weeks of dual blockade of PD1 and CTLA4 and 8 weeks of dual blockade of PD1 and LAG3, respectively in the NICHE2 and NICHE3 studies, and the pCR rates were 67% (72/107) and 79%, respectively." (PMID 38967817, 2024).
non-small cell lung carcinoma (50 papers, 2017 to 2025). A group of at least three distinct histological types of lung cancer, including non-small cell squamous cell carcinoma, adenocarcinoma, and large cell carcinoma. "Increased LAG-3 expression in T cells of patients with non-small cell lung cancer (NSCLC) has been associated with resistance to αPD-1 treatment and shorter progression-free survival." (PMID 36605214, 2022). "Moreover, elevated LAG-3 expression has been associated with reduced progression-free survival in patients with advanced non-small cell lung cancer treated with PD-1 blockade." (PMID 31681269, 2019). "Overexpression of LAG-3 and/or PD-1 has been observed in many human cancers, including melanoma, non-small cell lung cancer (NSCLC), colorectal cancer (CRC), breast cancer, and Hodgkin lymphoma." (PMID 40234667, 2025). "Published data from clinical trials with anti-LAG-3 monoclonal antibodies or bispecific antibodies in non-small-cell lung cancer." (PMID 40075753, 2025). "The current study, NCT05785767, is a randomized, double-blind, phase 2/3 study evaluating fianlimab (anti–LAG-3) plus cemiplimab (anti–PD-1) versus cemiplimab alone in the first-line treatment of advanced non-small-cell lung cancer." (PMID 40362333, 2025). "T-cell dysfunctionality was partially overcome ex vivo with PD-1 and LAG-3 co-blockade in T-cells from non-small cell lung cancer (NSCLC) patients, which recovered proliferative and effector activities." (PMID 39030301, 2024). "The clinicopathological correlations and prognostic significance of LAG-3 in non-small cell lung cancer are histotype-dependent, due to differences in the immune microenvironment between adenocarcinomas and squamous cell carcinomas." (PMID 36077354, 2022). "A previous study indicated that LAG-3 expression is closely related to a worse survival of patients with non-small cell lung cancer (NSCLC)." (PMID 34454491, 2021). "Higher levels of serum LAG-3 (sLAG-3) were found to correlate with earlier stages of non-small cell lung cancer." (PMID 34940257, 2021). "LAG3 accumulates on the surface of lymphocytes in various tumors, but is also found in the cytoplasm in non-small cell lung cancer (NSCLC) cells." (PMID 35111155, 2021). "In line with our data, LAG-3 expression may be a potential mechanism of immune evasion in PDAC, especially since in non-small cell lung carcinoma (NSCLC) prominent LAG-3 expression by T cells was associated with insensitivity to PD-1 blockade." (PMID 33803936, 2021). "Research in non-small-cell lung cancer (NSCLC) patients show elevated LAG-3 expression on Tregs residing in the tumor compared to Tregs found in peripheral blood and normal tissues." (PMID 33374804, 2020). "Consistent with our findings, previous studies showed that patients with positive or high density of LAG-3 had a poor survival in renal cell cancer and non-small cell lung cancer." (PMID 28977875, 2017). "In an unselected cohort of patients with stage I –IIIB non-small cell lung cancer, including mainly squamous cell carcinoma and adenocarcinoma but also other histological types such as adenosquamous and large cell carcinoma, LAG-3 expression on TILs was correlated with improved survival." (PMID 34442393, 2021). "We analyzed the variation of circulating immune suppressive-like cell subsets and exhausted immune cells in three non-small cell lung cancer patients treated with the combination of anti-CTLA-4 plus anti-PD-1 plus anti-LAG-3 at T0 (baseline), T1 (after 2 months) and T2 (after 4 months)." (PMID 34122429, 2021). "However, its role in immune escape is still controversial, as it has been described that LAG-3 expression in TILs is related to a positive prognosis in esophageal cancer, non-small cell lung cancer, Hodgkin’s lymphoma, and microsatellite instability-high colorectal cancer cases." (PMID 34067904, 2021).
non-small cell lung carcinoma (continued). "In addition, the research on T-cell showed that co-expression of PD-1, LAG-3 and TIM-3 was associated with prominent activation (CD69 expression) and effector function (GZMB level), as well as elevated levels of proapoptotic markers in non-small cell lung cancer." (PMID 39767624, 2024). "Relatlimab was the first anti-LAG-3 mAb that entered clinical testing, as a mono- or combination therapy with nivolumab, in melanoma, renal cell carcinoma and non-small cell lung carcinoma (NSCLC) (NCT019680109), and it showed to restored T-cell functionality." (PMID 35099641, 2022). "LAG-3+ TILs are prevalent in two broad histological subtypes of lung cancer: small cell lung cancer (SCLC) and non-small cell lung cancer (NSCLC), which include adenocarcinoma, squamous cell carcinoma and large cell carcinoma." (PMID 36077354, 2022). "The upregulation of checkpoint inhibitors LAG-3, TIM-3, TIGIT, and VISTA on T cells post anti-PD-L1 ICB has been described in many tumors, including melanoma and non-small cell lung carcinoma (NSCLC), as a mechanism for acquired resistance." (PMID 34322780, 2021). "Expression of LAG-3 can be found on cells in the tumor microenvironment (TME) of various solid tumors, including non-small cell lung cancer (NSCLC) and head and neck squamous cell carcinomas (HNSCC), and is commonly associated with a more aggressive tumor type and poor prognosis." (PMID 36859619, 2023). "In an open-label phase 2 trial, patients with non-small-cell lung cancer received neoadjuvant anti-PD-1 with or without anti-LAG-3, showing that curative intent surgery after combined blockade of PD-1 and LAG-3 is feasible, and leads to preliminary clinical responses." (PMID 38689060, 2024). "In an ongoing, open-label phase 2 study, 60 biomarker-unselected, treatment-naive patients with resectable non-small-cell lung cancer were randomized to receive two preoperative doses of nivolumab (anti-PD-1) with or without relatlimab (anti-LAG-3) antibody therapy." (PMID 38689060, 2024). "Unfortunately, the NCCN guidelines for the treatment of non-small-cell lung cancer from January 2025 do not indicate the place of drugs using the blockade of the TIGIT, TIM-3, or LAG-3 checkpoints." (PMID 40362333, 2025).
autoimmune disease (48 papers, 2014 to 2025). A disorder resulting from loss of function or tissue destruction of an organ or multiple organs, arising from humoral or cellular immune responses of the individual to their own tissue constituents. "Several studies have reported the role of LAG3 in the immunotherapy of neoplastic diseases, and some studies have also reported that LAG3 deficiency is involved in the pathogenesis of autoimmune diseases." (PMID 35265454, 2022). "On the basis of these findings, human LAG3+ Tregs are supposed to be specific to self-antigens associated with autoimmune disease; however, proving antigen specificity in human Tregs is difficult and remains to be elucidated." (PMID 28511719, 2017). "Abrogation of LAG-3 functions, either by administering anti-LAG-3 monoclonal antibody or by genetic ablation of LAG-3, results in an increased susceptibility to mercury-induced autoimmune disease." (PMID 25122007, 2014). "To investigate further the mechanisms by which LAG-3 influences the autoimmune disease, we compared the cytokine profile of LAG-3-deficient and wild-type B6.SJL mice which received 3 s.c. injections of HgCl2 on days 0, 2 and 4 or were left untreated." (PMID 25122007, 2014). "Conversely, adoptive transfer of wild-type CD4+ T cells was able to partially rescue LAG-3-deficient mice from the autoimmune disease." (PMID 25122007, 2014). "Loss-of-function of LAG-3 may cause unlimited T cell activation, proliferation and accelerate the progression of autoimmune diseases." (PMID 34975855, 2021). "The immune regulatory function of co-inhibitory receptors, including CTLA-4, PD-1, TIM-3, TIGIT, and LAG-3, was first discovered in the setting of autoimmune disease models, in which their blockade or deficiency resulted in induction or exacerbation of the disease." (PMID 31974523, 2020). "Contrary to findings in autoimmune disease and cancer, the blockade of LAG-3 increased the production of Th1-type tumor necrosis factor (TNF)-α and interferon (IFN)-γ, but decreased Th2-type and Treg-type IL-4, IL-10 and transforming growth factor (TGF)-β1." (PMID 41023624, 2025). "At present, there are 113 clinical trials worldwide focusing on LAG3, spanning a range of conditions, from advanced solid tumors and hematologic diseases to autoimmune disorders and chronic viral infections." (PMID 38592036, 2024). "LAG-3 also affects Tregs, which are critical for maintaining immune tolerance and preventing autoimmune diseases." (PMID 39660130, 2024). "The multiple functions of LAG-3 in the regulation of the immune system further emphasize its potential as a therapeutic target for autoimmune diseases and cancer." (PMID 39660130, 2024). "In the context of autoimmune disease, it is critical to consider the role of LAG-3 in maintaining immune homeostasis." (PMID 39331884, 2024). "The objective of this review is to examine the functions and molecular characteristics of LAG-3, as well as its current clinical applications in the context of tumor immune escape and autoimmune disease." (PMID 39331884, 2024). "Normally, LAG3 expressed on NK cells and activated T cells helps maintain immune homeostasis and prevents the occurrence of immune overreaction or autoimmune diseases." (PMID 39453075, 2024). "Our study revealed the possible capacity of LAG3+ B cells to maintain immune tolerance in autoimmune diseases, demonstrating their potential in RA activity evaluation and disease therapy." (PMID 37143367, 2023). "Despite emerging clinical trials with both agonistic and antagonistic antibodies targeting LAG-3, it is important to recognize that the knowledge of LAG-3 in relation to autoimmune disease is still rather limited." (PMID 35784333, 2022). "Due to the pivotal role of Lag-3 in immune regulation, several diseases including autoimmune diseases, cancer, chronic viral infection, and parasitic infection are correlated with aberrant Lag-3 expression." (PMID 36159789, 2022).